KRAS (KRas proto-oncogene, GTPase)
Diseases named in the same sentence as KRAS in open-access papers (continued):
Sharing a sentence is not in itself a finding about the gene and the disease.
metastatic colorectal cancer (continued). "Considering the fact that these agents are now established treatment options in metastatic colorectal cancer and widely used, identification of genetic determinants of primary resistance in KRAS wild type tumour would be essential to further development." (PMID 21439039, 2011). "Several studies indicate greater benefit from a Cetuximab therapy for EGFR expressing metastatic colorectal cancer patients with KRAS wild type." (PMID 21197450, 2010). "KRAS mutational analysis is a genetic test used in clinical practice for determining the status of the KRAS gene (wild type or mutant) in tumors from patients with metastatic colorectal cancer (CRC)." (PMID 20877448, 2010). "We address the prognostic and predictive value of KRAS, PIK3CA and BRAF mutations for clinical outcomes in response to active agents in the treatment of metastatic colorectal cancer (mCRC)." (PMID 19603024, 2009). "KRAS codons 12 and 13 mutations predict resistance to anti-EGFR monoclonal antibodies (moAbs) in metastatic colorectal cancer." (PMID 19603018, 2009). "Inhibitors of the oncogene KRAS hold promise for treating metastatic colorectal cancer (mCRC)." (PMID 41128661, 2026). "Systemic treatment for metastatic colorectal cancer relies on cytotoxic chemotherapy with the addition of monoclonal antibodies targeting angiogenesis or the tyrosine kinase receptor EGFR for patients with a wild-type KRAS oncogene." (PMID 40004631, 2025). "This implies that the interaction between immune regulation and EGFR signaling may influence how the KIR–HLA profile predicts treatment outcomes in KRAS-WT metastatic colorectal cancer patients." (PMID 40869384, 2025). "Another Phase Ib clinical trial of onvansertib combined with FOLFIRI and bevacizumab showed a manageable safety profile and a promising response rate compared with the historical response rate to FOLFIRI/bevacizumab in patients with KRAS-mutant metastatic colorectal cancer (mCRC)." (PMID 41458961, 2025). "In this multicenter study of 2458 metastatic colorectal cancer (mCRC) patients across Turkey, we found that KRAS mutations were present in 45% of cases, with no significant regional variation." (PMID 40282985, 2025). "Similarly, in metastatic colorectal cancer, biomarker testing for KRAS/NRAS, BRAF V600E, MSI, HER2, and NTRK fusions is essential for selecting systemic therapy and clinical trials." (PMID 41462880, 2025). "In the following year, phase III clinical trials brought great encouragement to the anti-EGFR therapy by suggesting that FOLFIRI plus cetuximab might be preferred for patients with metastatic colorectal cancer that is KRAS exon 2 wild-type." (PMID 38706597, 2024). "Contrastingly, mOS decreased by approximately 2 months in patients with other KRAS mutations, once cetuximab was added to the regimen, thus indicating KRAS G13D conferred the most favourable prognosis in metastatic colorectal cancer patients treated with cetuximab and chemotherapy." (PMID 39372214, 2024). "Furthermore, the PFS of Divarasib with cetuximab extended to 8.1 months, representing the longest duration among all KRAS G12C inhibitor clinical trials for metastatic colorectal cancer." (PMID 39770538, 2024). "Highlighted examples include chr20q amplifications in CMS2 and KRAS mutations in CMS4, which may optimise patient stratification for metastatic colorectal cancer." (PMID 37666855, 2023). "Keywords like overall survival, neoadjuvant chemoradiotherapy, locally advanced rectal cancer, robotic surgery, anastomotic leakage, chemoradiotherapy, metastatic colorectal cancer, KRAS, meta-analysis, colorectal surgery, and laparoscopic surgery were studied." (PMID 36827037, 2023). "Thus, in this study, the two SPs, SPK1 and its derivative SPKM19, were employed for the secretion of two therapeutic KRAS mimotopes, 68V-DT and wild-type KRAS, in developing L. lactis as a potential mucosal vaccine against metastatic colorectal cancer." (PMID 37240273, 2023).
metastatic colorectal cancer (continued). "Cetuximab, a monoclonal antibody that binds the extracellular domain of epidermal growth factor receptor (EGFR), is effective in KRAS wild-type metastatic colorectal cancers but not in KRAS mutations." (PMID 37513471, 2023). "There is no targeted therapy for KRAS proto‐oncogene, GTPase (KRAS)‐mutant metastatic colorectal cancer (mCRC) because the underlying mechanism remains obscure." (PMID 36453019, 2023). "Despite these limitations, our study contributes to the growing body of evidence indicating that the KRAS p.G12C mutation is a strong negative prognostic factor in metastatic colorectal cancer." (PMID 37509241, 2023). "KRAS mutations, present in over 40% of metastatic colorectal cancer (mCRC), are negative predictive factors for anti-EGFR therapy." (PMID 35251991, 2022). "Another recent study aimed to determine how KRAS, NRAS and BRAF mutations in hematopoietic cells may alter the results of liquid biopsies in patients with metastatic colorectal cancer." (PMID 35127745, 2021). "The panitumumab or cetuximab monotherapy (ASPECCT) was the first head-to-head, randomised, phase-III study of panitumumab versus cetuximab for the treatment of chemotherapy-refractory wild-type KRAS exon 2 metastatic colorectal cancer (February 2010 to July 2012)." (PMID 32605298, 2020). "Thus, the aim of this study is to evaluate the role of KRAS and BRAF mutations as prognosis factors and predictive biomarkers for 1st line standard chemotherapy in metastatic colorectal cancer." (PMID 31952366, 2020). "Some clinical data indicate that the efficacy of cetuximab may be reduced for patients with wild-type KRAS exon 2 metastatic colorectal cancer who previously received bevacizumab." (PMID 32605298, 2020). "The efficacy of ATT has been demonstrated in a xenograft mouse model and a metastatic colorectal cancer patient by targeting non-spliced epitopes carrying KRAS G12D mutations and presented by HLA-A*11:01 or -C*08:02 molecules, respectively." (PMID 31803176, 2019). "Cetuximab is a standard-of-care treatment for RAS wild-type metastatic colorectal cancer (mCRC) but not for those harbor a KRAS mutation since MAPK pathway is constitutively activated." (PMID 30796344, 2019). "KRAS mutated circulating tumor DNA (MctDNA) can be monitored in the blood of patients with metastatic colorectal cancer (mCRC), but dynamic changes have not been determined." (PMID 29849949, 2018). "Research has found that inhibition of HER2/neu activity may help in treating metastatic colorectal cancer and tumors with mutant KRAS." (PMID 27965461, 2017). "The American Society of Clinical Oncology (ASCO) published guidelines in 2009 recommending all patients with metastatic colorectal cancer (mCRC) receive KRAS testing to guide anti-epidermal growth factor receptor (anti-EGFR) monoclonal antibody (MoAb) treatment." (PMID 29202108, 2017). "For metastatic colorectal cancer, mutations in exons 2/3/4 of the GTPases KRAS and NRAS are negative predictive biomarkers for efficacy of cetuximab and panitumumab." (PMID 28456787, 2017). "We enrolled 50 patients with wild-type KRAS metastatic colorectal cancer." (PMID 29354119, 2017). "In patients with metastatic colorectal cancer, KRAS mutation is a negative predictive marker for anti-EGFR therapy." (PMID 29228748, 2017). "KRAS mutations are an established predictor of lack of response to EGFR-targeted therapies in patients with metastatic colorectal cancer (mCRC)." (PMID 27636997, 2016). "KRAS mutation testing is mandatory in the management of metastatic colorectal cancer prior to treatment with anti-EGFR antibodies as patients whose tumors express mutant KRAS do not benefit from these agents." (PMID 27485514, 2016). "In patients with metastatic colorectal cancer treated with CT or best supportive care (BSC), the OS was 6.1 vs. 4.6 months, but when the KARS mutation is taken in account, there is an OS increase for a wide-type KRAS patients, 8.6 vs. 5.0 months." (PMID 27050148, 2016).
metastatic colorectal cancer (continued). "Sixty-two patients with previously untreated KRAS/BRAF wild-type metastatic colorectal cancer were recruited to the study between April 2010 and May 2011." (PMID 26467662, 2015). "Biweekly administration of cetuximab requires only one hospital visit every 2 weeks, and may become a convenient treatment option for patients with KRAS/BRAF wild-type metastatic colorectal cancer." (PMID 26467662, 2015). "Recent studies showed that other activating mutations in KRAS (exons 3 and 4) or NRAS (exons 2, 3 and 4), in addition to KRAS mutation in exon 2 are also associated with poor prognosis or resistance to anti-EGFR antibody in metastatic colorectal cancer." (PMID 25954997, 2015). "The combination of FOLFOX-4 and Cetuximab has also been demonstrated to be effective with regard to response rate (57 to 81 %) and progression-free survival with good tolerance, in patients with non-mutated KRAS (wild-type) metastatic colorectal cancer." (PMID 26156156, 2015). "These drugs were initially proved to be effective only in a subgroup of metastatic colorectal cancer (mCRC) carrying a wild-type KRAS gene in codons 12 and 13 of exon 2 and in 2009 received the European Medicines Agency (EMA) approval for this molecularly selected group of mCRC patients." (PMID 26335936, 2015). "Characteristics of anti-EGFR treated KRAS wild type metastatic colorectal cancer patients." (PMID 24940619, 2014). "However, only about half of metastatic colorectal cancer patients with wild-type KRAS tumors respond to anti-EGFR treatment 9, indicating a need for additional biomarkers of treatment response." (PMID 24890702, 2014). "Since the KRAS mutation is not responsible for all metastatic colorectal cancer (mCRC) patients with resistance to anti-epidermal growth factor receptor (EGFR) monoclonal antibody (MoAb) therapy, new predictive and prognostic factors are actively being sought." (PMID 24500024, 2014). "Instability in KRAS has also been described for metastatic colorectal cancer." (PMID 25523272, 2014). "With approximately two-thirds of metastatic colorectal cancer patients being wild-type KRAS, this marker could help better use EGFR therapy and spare patients from inappropriate treatment." (PMID 25243170, 2014). "The idea of personalized medicine was introduced to the treatment of metastatic colorectal cancer (mCRC) when KRAS codon 12/13 mutations were identified as negative predictors of anti-EGFR-antibody (EGFR-mAB) treatment." (PMID 24816724, 2014). "In addition, low DEK expression level predicted irinotecan-based chemotherapy response in metastatic colorectal cancer patients with KRAS wild-type." (PMID 25515240, 2014). "First, systematic KRAS genotyping in metastatic colorectal cancer patients might be hampered in the future, at least for some patients, by the difficulty of obtaining tumor samples suitable for molecular analyses." (PMID 24884535, 2014). "We compared morphologic computed tomography (CT)-based to metabolic fluoro-deoxy-glucose (FDG) positron emission tomography (PET)/CT-based response evaluation in patients with metastatic colorectal cancer and correlated the findings with survival and KRAS status." (PMID 24941936, 2014). "Epidermal growth factor receptor (EGFR) monoclonal antibody was approved for treatment of metastatic colorectal cancer patients without KRAS mutations." (PMID 23874486, 2013). "It has been approved to treat KRAS wild-type metastatic colorectal cancer and head and neck cancer." (PMID 23286345, 2013). "The pooled analysis of the CRYSTAL and OPUS trials on metastatic colorectal cancer showed that BRAF mutation was not predictive for treatment with cetuximab in KRAS wild-type patients, but indicated poor prognosis." (PMID 24298448, 2013).
metastatic colorectal cancer (continued). "Cetuximab and panitumumab are effective epidermal growth factor receptor (EGFR) targeted agents for metastatic colorectal cancer (mCRC), but patients whose tumors have KRAS mutations except G13D are generally believed to not benefit from these agents." (PMID 23671647, 2013). "Novel strategies that target the epidermal growth factor receptor (EGFR) have led to the clinical development of monoclonal antibodies, which treat metastatic colorectal cancer (mCRC) but only subgroups of patients with increased wild type KRAS and EGFR gene copy, respond to these agents." (PMID 23144978, 2012). "In metastatic colorectal cancer, objective response to anti-EGFR antibody therapy can be expected in a third of unselected patients, and conversely, tumor KRAS mutations may be found in almost a third of responders." (PMID 23226389, 2012). "KRAS mutation is a negative predictive factor for treatment with anti-epidermal growth factor receptor (EGFR) antibodies in metastatic colorectal cancer (mCRC)." (PMID 22804917, 2012). "Recent studies have reported associations between a variant allele in a let-7 microRNA complementary site (LCS6) within the 3′untranslated region (3′UTR) of KRAS (rs61764370) and clinical outcome in metastatic colorectal cancer (mCRC) patients receiving cetuximab." (PMID 23167843, 2012). "KRAS mutation is a negative predictive factor for treatment with anti-epidermal growth factor receptor antibody in metastatic colorectal cancer (CRC)." (PMID 21364579, 2011). "Results of the CRYSTAL trial indicate that the clinical activity of cetuximab against metastatic colorectal cancer is enhanced in patients with wild-type KRAS compared with individuals having KRAS mutations, none of whom benefited from cetuximab treatment." (PMID 22123319, 2011). "Our aim was to investigate the prognostic and predictive value of the oncogenic MAPKK-like protein T-cell-originated protein kinase (TOPK) stratified by KRAS and BRAF mutations in patients with sporadic, hereditary and metastatic colorectal cancer (CRC) treated with anti-EGFR therapy." (PMID 19935791, 2010). "In human tumors, the RAS signature is coherent across multiple tumor types, is elevated in clinical subtypes not known to harbor KRAS mutations (i.e. ER negative breast cancer), and predicts resistance to cetuximab in metastatic colorectal cancer." (PMID 20591134, 2010). "KRAS codons 12 and 13 activating mutations are widely recognised as predictors of resistance to the treatment with anti-EGFR monoclonal antibodies (moAbs) in metastatic colorectal cancer (mCRC) patients." (PMID 19603018, 2009). "The impact of KRAS mutations on cetuximab sensitivity in epidermal growth factor receptor fluorescence in situ hybridisation-positive (EGFR FISH+) metastatic colorectal cancer patients (mCRC) has not been previously investigated." (PMID 18577988, 2008). "Knowing that HER2 could also represent an important therapeutic target in KRAS wild-type metastatic colorectal cancer patients resistant to anti-EGFR treatment, the authors determined the prevalence rate for HER2 amplification in KRAS wild-type samples, which were almost identical (5.1% and 5.2%)." (PMID 36143438, 2022). "Thus, the combination of the CCR7 function-blocking antibody along with a p-AKT antagonist may serve as a platform for a therapeutic against KRAS-expressing metastatic colorectal cancer." (PMID 35203305, 2022). "With parameter values fitted to the data or informed by literature data, the model could capture previously reported tumor burden dynamics and mutant KRAS levels in circulating tumor DNA (ctDNA) of patients with metastatic colorectal cancer treated with panitumumab." (PMID 35273301, 2022).
metastatic colorectal cancer (continued). "Similarly, FOLFIRI is also being tested in combination with the virus based investigative therapy REOLYSIN and bevacizumab in FOLFIRI naïve patients with KRAS mutant metastatic colorectal cancer (Clinicaltrials.gov Identifier: NCT01274624 (accessed on 24 February 2021))." (PMID 33801965, 2021). "Additionally, it may be a potential biomarker for patients carrying wild-type KRAS in metastatic colorectal cancer." (PMID 33989111, 2021). "This has been shown for the KRASG12D mutation in a patient with metastatic colorectal cancer, and we observed that repetitive exposure to autologous tumour cells can result in enrichment of KRAS-specific T cells that was non-detectable in the ‘young’ TILs population." (PMID 30377343, 2019). "Our objective was the determine the frequency of most common mutations in KRAS gene (p.G12D, p.G12V, p.G12A, p.G12C, p.G12S, p.G12R, p.G13D, p.Q61H, p.Q61L, p.Q61R, p.A146T, p.A146V, p.A146P) together with the BRAF V600E mutation in Albanian patients with metastatic colorectal cancer." (PMID 25267307, 2014). "Our study indicates that, if a tumor sample is unavailable or insufficient, using a more sensitive method than PNA-PCR assay such as ultra deep sequencing technology on a plasma DNA sample might be an alternative way to determine KRAS status in metastatic colorectal cancer." (PMID 25491325, 2014). "Similarly, the anti-EGFR antibody cetuximab was associated with significant worsening of outcome when added to standard therapy in the treatment of KRAS-mutant metastatic colorectal cancer, while it may improve outcome in KRAS-wild-type patients." (PMID 23587187, 2013). "While the predictive value of wild-type KRAS genotype for identifying patients who will benefit from anti-EGFR monoclonal antibodies treatment is now well established in metastatic colorectal cancer, the significance of KRAS and BRAF mutations in NSCLC is not yet comparably clear." (PMID 23930206, 2013). "The aim of the present study was to investigate the clinical value of triple KRAS, BRAF and PIK3CA mutational testing by commercially available kits combined with immunohistochemical testing of EGFR and PTEN loss in a material of patients with metastatic colorectal cancer." (PMID 21439039, 2011). "The presence of KRAS alterations at the time of resistance to anti-HER2 therapy is consistent with recent data from a clinical trial of trastuzumab and lapatinib in metastatic colorectal cancer." (PMID 38406801, 2024). "The more recent MOUNTAINEER trial, a phase II study, compared the combination of tucatinib plus trastuzumab to tucatinib alone in patients with locally advanced or metastatic colorectal cancer (CRC) refractory to chemotherapy and with wild-type KRAS." (PMID 39682117, 2024). "In metastatic colorectal cancer, RMST has been used to evaluate progression-free survival and overall survival across different treatment strategies for KRAS wild-type and KRAS mutant patients." (PMID 39458124, 2024). "Lapatinib and cetuximab can be used as a reference for the treatment of KRAS wild-type, HER2-positive metastatic colorectal cancer in a long-term clinical trial." (PMID 37670166, 2023). "The aim of this study was to investigate the effects of baseline plasma AREG levels in KRAS, NRAS, and BRAF wild-type metastatic colorectal cancer (CRC) on treatment outcome with palliative first-line cetuximab + FOLFIRI chemotherapy." (PMID 34893673, 2021). "This all-in-one strategy is particularly relevant for metastatic colorectal cancer cases whose MSI status contributes to tumour prognosis and patient selection for immunotherapy while KRAS, NRAS and BRAF genotyping helps for targeted therapies decision." (PMID 33009475, 2020). "Cetuximab was approved by the FDA for metastatic colorectal cancer (CRC) and KRAS wild-type CRC in 2004 and 2009, respectively." (PMID 32793499, 2020).